MCL1 (MCL1 apoptosis regulator, BCL2 family member)
Diseases named in the same sentence as MCL1 in open-access papers (continued):
Sharing a sentence is not in itself a finding about the gene and the disease.
melanoma (continued). "Development and progression of malignant melanoma mainly result from dysfunction of pro- and antiapoptotic Bcl-2 family proteins, especially antiapoptotic Mcl-1 protein." (PMID 31432325, 2020). "The power of combination approaches with BH3-mimetics in melanoma is further supported by another recent study that investigated mRNA and protein expression levels of MCL-1 and BCL-xL in different cancer models." (PMID 33308268, 2020). "Taken together, it seems that the Mcl-1 protein inhibition is necessary and sufficient to exterminate melanoma cells." (PMID 31432325, 2020). "Overall, our study supports the rationale for combining an MCL1 inhibitor with a BCL2 inhibitor as a therapeutic option in patients with advanced melanoma." (PMID 32764384, 2020). "To confirm that key pro-survival proteins targeted by BH3-mimetics (BCL-2, BCL-XL, MCL-1) were expressed in more clinically-relevant patient-derived tissue, we performed immunohistochemistry on 127 biopsies from melanoma patients with Stage III/IV disease." (PMID 31019203, 2019). "Here, we show that uniquely low BCL-XL expression in melanoma biases the pro-survival pool towards MCL1." (PMID 31727888, 2019). "In summary, our results demonstrate that targeting melanoma’s MCL1 bias unleashes the potential of BRAF and ERK1/2 pathway inhibitors by transforming cytostatic responses into striking apoptotic cell death." (PMID 31727888, 2019). "Our studies showed that MCL-1 and BCL-XL must be co-targeted to achieve the most effective melanoma cell killing, though co-operativity was also observed by co-targeting MCL-1 and BCL-2." (PMID 31019203, 2019). "The ABT-263 and A1331852 combination data closely mirrored each other, suggesting that the critical proteins for melanoma cell survival are MCL-1 and BCL-XL, although BCL-2 has some involvement." (PMID 31019203, 2019). "The pro-survival members, BCL-2, BCL-XL, BCL-W, MCL-1 and BFL-1, have all been implicated in melanoma survival and chemoresistance." (PMID 31019203, 2019). "This study shows that the pro-survival pool is biased towards MCL1 in melanoma so that BRAF or MEK1/2 inhibitors are synthetic lethal with the MCL1 inhibitor AZD5991, improving tumour growth inhibition." (PMID 31727888, 2019). "Conversely, we observed minimal change in MCL-1 dependence in cells derived from a patient with a BRAF-mutant melanoma who had developed resistance to BRAF/MEK inhibitors." (PMID 31727958, 2019). "Mechanistic studies demonstrated that ERK1/2 inhibition primes melanoma cells to undergo apoptosis following subsequent MCL1 inhibition." (PMID 31727888, 2019). "MCL1 levels were similar across the four lineages but higher in melanoma (~20 vs. <14 fmol per μg total cellular protein)." (PMID 31727888, 2019). "Mcl-1 expression is enhanced in melanoma cells compared with melanocytes and upregulated by the B-RAF-MEK-extracellular signal-regulated kinase pathway through the control of Mcl-1 protein turnover." (PMID 31275384, 2019). "Here, we show that the pro-survival BCL2 family pool is biased towards MCL1 in melanoma compared to CRC, NSCLC and pancreatic tumour lineages, due to low BCL-XL expression." (PMID 31727888, 2019). "This was confirmed by western blotting and absolute protein quantification, which revealed that low BCL-XL expression biased the pro-survival protein pool strongly towards MCL1 in melanoma." (PMID 31727888, 2019). "Conversely, interruption of this mechanism of anti-apoptotic adaptive resistance (via the use of MCL-1 inhibitors) dramatically increased cytotoxic responses in vitro and in murine melanoma models." (PMID 31727958, 2019). "Interrogation of CCLE and TCGA data sets indicated that the median MCL1:BCL-XL mRNA ratio was two- to fourfold higher in melanoma than in CRC, NSCLC and pancreatic cancer lineages." (PMID 31727888, 2019). "To independently test the results from this screen, we treated the BRAF-mutant melanoma cell line A375M with siRNA targeting the non-coding region of MCL1." (PMID 31727958, 2019).
melanoma (continued). "All melanoma cell lines exhibited strikingly lower BCL-XL expression than the CRC cell lines whereas MCL1 was, on the whole, marginally higher in melanoma." (PMID 31727888, 2019). "Since melanoma has high levels of Mcl-1 expression, these cells have resistance to ABT-737 (a selective inhibitor of Bcl-2, Bcl-xL, and Bcl-w)-induced apoptosis." (PMID 30463333, 2018). "Combined treatment with maritoclax and ABT-737 enhances apoptosis through downregulation of Mcl-1 expression in melanoma cells." (PMID 30463333, 2018). "For example, CUR induced apoptosis via the upregulation of the proapoptotic Bax and the downregulation of the antiapoptotic proteins such as myeloid cell leukemia 1 (Mcl1) and Bcl2 in human melanoma cells." (PMID 29743988, 2018). "Some studies on melanoma have shown that STAT3 increases the expression of antiapoptotic genes Bcl-xl, Mcl-1 and further promote melanoma proliferation and malignant transformation." (PMID 29348670, 2018). "MCL1 is involved in melanoma cell survival and its expression is increased in melanoma cells compared to primary melanocytes." (PMID 30197759, 2018). "Pharmacological inhibition or downregulation of MCL-1 promotes apoptosis and/or overcome drug resistance in multiple cancers, including melanoma, making it a high-priority therapeutic target." (PMID 30185782, 2018). "Other authors observed increased MCL1 expression induced by oncogenic BRAF in melanoma, thereby inducing a more aggressive phenotype." (PMID 30197759, 2018). "This study is the first to test the effectiveness of A-1210477 (a potent MCL-1 inhibitor) in combination with ABT-263 (the BCL-2/BCL-W/BCL-XL inhibitor) in melanoma." (PMID 30185782, 2018). "Here, our result suggest that the combination of ABT-263 with a direct and potent MCL-1 inhibitor is a promising approach for treating melanoma." (PMID 30185782, 2018). "In melanoma, BRAF mutations can result in enhanced MCL1 levels, thereby increasing resistance to apoptosis." (PMID 30197759, 2018). "We have also attempted to make MCL-1-null lines using CRISPR/Cas9 in three different melanoma cell lines using three different gRNAs against MCL-1." (PMID 27086916, 2017). "The results also included 10 SNPs previously identified for melanoma risk reported at MC1R (2 SNPs), MX2, TERT/CLPTM1L, PLA2G6, CASP8, ACTRT3, ASIP, CDC91L1, and ARNT/SETDB1/LASS2ANXA9/MCL1/CTSK." (PMID 27993549, 2017). "Our results are in accordance with studies on the bortezomib effect in different melanoma cell lines, which revealed a rapid increase in Mcl-1 expression at first and then its reduction to or below basal levels." (PMID 28281027, 2017). "Here we examined the effects of the MCL-1 inhibitor SC-2001 in killing non melanoma-initiating-cells (bulk of melanoma), and melanoma-initiating-cells (MICs)." (PMID 27086916, 2017). "In this study, demethylzeylasteral, an extract of Tripterygium wilfordii Hook F,49 is proved to inhibit cell proliferation as well as inhibit MCL1 expression in melanoma cells." (PMID 29072681, 2017). "It has been postulated that the key elements of bortezomib-induced apoptosis in melanoma cells are Bcl-2 family members—proapoptotic Noxa and antiapoptotic Mcl-1." (PMID 28281027, 2017). "And up-regulation of Mcl-1 is critical for survival of human melanoma cells upon endoplasmic reticulum stress." (PMID 29137317, 2017). "In summary, the data presented here suggests that MCL-1 is a promising target for treating melanomas and that SC-2001 is effective at killing non-melanoma-initiating cells." (PMID 27086916, 2017). "Consistent with other reports we found higher endogenous MCL-1 expression in most melanomas compared to melanocytes in both cell lines and tumor samples from patients." (PMID 27086916, 2017). "These mean demethylzeylasteral inhibits clonogenicity of melanoma cells in vitro and the inhibition can be retrieved by overexpression of MCL1." (PMID 29072681, 2017).
melanoma (continued). "Although indirect, this data further supports the idea that MCL-1 is essential for the survival of melanoma cells and is therefore an attractive therapeutic target for melanoma." (PMID 27086916, 2017). "We and others have shown that the knockdown of MCL-1 sensitizes melanoma cells to various treatments, including BRAF or MEK inhibitors and thus, targeting MCL-1 can be a new alternative for melanoma treatment." (PMID 27086916, 2017). "As with melanoma cells, we have found that both survivin and Mcl-1 declined after ADI-PEG20 treatment and further decreased upon combination treatment." (PMID 28587170, 2017). "Oncogenic activation of BRAF signaling in melanoma upregulates MCL-1 expression and contributes to increased resistance to BRAF/MEK inhibitors and overall tumor progression and survival." (PMID 27086916, 2017). "After demethylzeylasteral treatment, MCL1 is repressed and then induces apoptosis in melanoma cells." (PMID 29072681, 2017). "Epoxomicin treatment also resulted in accumulation of Bcl-2 family members—proapoptotic Noxa and antiapoptotic Mcl-1, which were postulated as the targets for bortezomib in melanoma." (PMID 28281027, 2017). "In melanoma cells, overexpression of miR-193b reduced Mcl-1 expression and sensitised these cells to ABT-737 (BH3 mimetic) induced apoptosis." (PMID 26878873, 2016). "IT treatment (20, 40 and 80 μM) for 72 h markedly decreased the levels of survivin, BCL-XL, and MCL-1 in human melanoma A375S, A375R, A2058, and MEWO cells." (PMID 27323414, 2016). "Multiple labs including our own have repeatedly shown that NOXA/MCL-1/BCL-2 apoptotic node is a common vulnerable spot for targeting the heterogeneous cell population of melanoma." (PMID 27829238, 2016). "BRAFV600 has been shown to not only stabilize the MCL-1 protein, but to induce MCL-1 transcription through activation of STAT3, rendering melanoma cells susceptible to apoptosis via STAT3 suppression." (PMID 27846237, 2016). "Accordingly, MCL-1 was often highly expressed in melanomas, and when knocked down diminished oncogenic potential." (PMID 27846237, 2016). "Then the wildtype-MCL-1 3′ UTR and mutant-MCL-1 3’UTR were transfected into WM3928 human melanoma cells." (PMID 27846237, 2016). "We report here for the first time that miR-32 behaves as a tumor suppressor miRNA in melanoma by inhibiting the expression of MCL-1, as well as its upstream effectors NRAS and PI3K." (PMID 27846237, 2016). "Wild type A375 and SK-MEL-28 melanoma cells completely lost sensitivity to BRAF inhibitors alone or in combination with MEK1/2 inhibitors upon Mcl-1 overexpression and transformed them into resistant cells." (PMID 26497853, 2015). "The combination of Noxa overexpression or Mcl-1 decrease strongly sensitized melanoma cells to ABT-737." (PMID 26304929, 2015). "Mcl-1 targeted therapies will have significant impact on the patients with melanoma tumors refractory to BRAF inhibitors alone or in combination with MEK1/2 inhibitor." (PMID 26497853, 2015). "Inhibition of MCL-1 preceding transfer to serum-containing medium caused the induction of cell death in a subset of melanoma cells, which confirms the involvement of MCL-1 in melanoma cell survival during the rapid alteration of growth conditions." (PMID 26035829, 2015). "Further results showed that MCL-1 was directly regulated by miR-193b, which is in accordance with the prior finding in melanoma." (PMID 26526790, 2015). "MCL-1 is also an adaptive contributor protecting melanoma cells from the ER stress-induced cell death." (PMID 26035829, 2015). "High levels of MAPK and/or PI3K signaling typical in melanoma increase levels of anti-apoptotic Bcl-2, Mcl-1, Bcl-XL, survivin and XIAP while suppressing expression of the potent apoptotic inducer Bim and sequestering pro-apoptotic Bmf to the cytoskeleton." (PMID 26426052, 2015).
melanoma (continued). "MCL-1 half-life can be prolonged, however, upon ERK-1/2-dependent phosphorylation of MCL-1 at Thr163, and this effect has been also reported in melanoma cells." (PMID 26035829, 2015). "The expressions of Mcl-1 were examined in a panel of melanoma cell lines with different sensitivity before and after treatment with EGb761." (PMID 25860257, 2015). "For example, downregulation of miR-15a, which is observed in several cancers including melanoma, led to an overexpression of several oncogens, such as Bcl-2, Cyclin D1, and Mcl-1." (PMID 26631117, 2015). "We further treated eight other melanoma cell lines with 0.4 μM vemurafenib and observed significant upregulation of Mcl-1 in all the cell lines." (PMID 26497853, 2015). "The significance of Mcl-1 in regulating EGb761-induced apoptosis of melanoma cells was further demonstrated by siRNA knockdown of Mcl-1." (PMID 25860257, 2015). "A growing body of evidence has demonstrated that sorafenib induces apoptosis in melanoma cells by activating pro-apoptotic proteins (Bad, Bak and Bax), down-regulating anti-apoptotic proteins (Bcl2, Bcl-Xl and Mcl-1) and inducing PARP cleavage." (PMID 26299806, 2015). "XL888 induced apoptosis of vemurafenib-resistant melanoma cells by increasing FoxO3a-induced Bim transcription and downregulation of Mcl-1." (PMID 26405162, 2015). "Vemurafenib treatment was able to induce a modest 2 fold increase in apoptosis in both the melanoma cell lines with stable Mcl-1 overexpression in contrast to 6 fold induction of apoptosis in the respective parent cell lines." (PMID 26497853, 2015). "Further studies on a panel of melanoma cell lines demonstrated that EGb761 downregulated Mcl-1 in all the sensitive cell lines, but increased Mcl-1 in all the resistant cell lines." (PMID 25860257, 2015). "Melanoma cells resistant to BRAF inhibitors showed massive expression of Mcl-1 as compared to respective sensitive cell lines." (PMID 26497853, 2015). "Unlike dinaciclib, maritoclax has been shown to specifically target MCL-1 for proteasomal degradation in experimental models of melanoma and various haematological malignancies." (PMID 26059440, 2015). "Our results conclusively establish that overexpression of Mcl-1 is critical for melanoma cell survival in the setting of BRAF inhibitor treatment and induce clinical resistance to BRAF inhibitors." (PMID 26497853, 2015). "Taken together, these results indicate that Mcl-1 is a key regulator of apoptosis induced by EGb761 in melanoma cells." (PMID 25860257, 2015). "As expected, dabrafenib resistant melanoma cells showed marked upregulation of Mcl-1 as compared to the respective wild type (sensitive) cells." (PMID 26497853, 2015). "Altogether, these results suggest that the increased stability of MCL-1 transcript is a mechanism used transiently by melanoma cells during their immediate response to changes in the microenvironment." (PMID 26035829, 2015). "GX15-070 is a small-molecule inhibitor of Mcl-1 and was shown to overcome Mcl-1-mediated resistance in oral carcinoma and murine melanoma cells." (PMID 26008975, 2015). "Taken together, these results demonstrate that EGb761 kills melanoma cells through the mitochondrial apoptotic pathway, and that Mcl-1 is a major regulator of sensitivity of melanoma cells to apoptosis induced by EGb761." (PMID 25860257, 2015). "Similar results were observed when Mcl-1 overexpressing melanoma cells were treated with a combination of vemurafenib and trametinib." (PMID 26497853, 2015). "ABT-737 inhibits Bcl-2; Bcl-w and Bcl-XL but melanoma cells are typically protected from the cytotoxic effects of ABT-737 by high levels of Mcl-1." (PMID 26304929, 2015). "We have found that MCL-1 was the only pro-survival protein which was overexpressed in all melanoma populations when compared to melanocytes." (PMID 26035829, 2015).
melanoma (continued). "One of these inhibitors is marinopyrrole A (maritoclax), which directly binds MCL-1 and targets it for proteasomal degradation in various haematological cancer cells and some melanoma cells." (PMID 26059440, 2015). "Single treatment of BRAF mutant melanoma cell lines with vemurafenib or dabrafenib (BRAF inhibitors) alone or in combination with trametinib (MEK1/2 inhibitor) resulted in overexpression of Mcl-1." (PMID 26497853, 2015). "Similar to our results in PCa cells, it was found that endoplasmic reticulum stress induced up-regulation of MCL1 and rendered melanoma cells more sensitive to Obatoclax treatment." (PMID 25749045, 2015). "Our studies provided several in vitro and in vivo evidences to prove this and established Mcl-1 as the major culprit in inducing resistance to BRAF inhibitors in melanoma." (PMID 26497853, 2015). "In this study, we have established that resistance to BRAF inhibitors such as vemurafenib or dabrafenib alone or in combination with MEK1/2 inhibitor (trametinib) in melanoma cells was due to overexpression of Mcl-1." (PMID 26497853, 2015). "Silencing of Mcl-1 using siRNA completely sensitized resistant melanoma cells to growth suppression and induction of apoptosis by BRAF inhibitors." (PMID 26497853, 2015). "A survey of antiapoptotic Bcl-2 family member expression in breast, brain, colon, lung, ovarian, renal and melanoma cell lines revealed that Mcl-1 mRNA is more abundant than Bcl-2 or Bcl-xL." (PMID 24529193, 2014). "Overexpression of Mcl-1 was found in malignant melanoma compared to benign nevi and increased expression of Mcl-1 was also observed by comparing primary and metastatic melanoma samples utilizing a tissue microarray." (PMID 24529193, 2014). "The down regulation of Mcl-1 has been shown to sensitize neuroblastoma cells to cytotoxic chemotherapy and resistant melanoma cells to Fas mediated apoptosis." (PMID 25409302, 2014). "Treatment with MEK/ERK inhibitor U0126 resulted in Mcl-1 downregulation and induced marked apoptosis in Mel-RM melanoma cells." (PMID 24529193, 2014). "In particular, in melanoma cells, we demonstrate that PG disrupts the interaction between MCL-1 and BAK, allowing the formation of BAK/BAX complex and the subsequent cytochrome c release to the cytosol, which mediates the mitochondrial apoptosis activation." (PMID 23460874, 2013). "Anti-apoptotic Bcl-2 family proteins, in particular, Mcl-1, are known to play a critical role in resistance of human melanoma cells to induction of apoptosis by endoplasmic reticulum stress and other agents." (PMID 24367627, 2013). "In particular, the ability of dinaciclib to regulate these anti-apoptotic proteins is likely to be of great utility in melanoma where overexpression of XIAP, Bcl-2 and Mcl-1 is commonplace and can contribute to melanoma chemoresistance." (PMID 23527225, 2013). "We have previously shown that activation of the unfolded protein response (UPR) in melanoma cells can result in upregulation of Mcl-1 at the transcriptional level, a protective response to induction of ER stress." (PMID 24367627, 2013). "Although ABT-737 is the most potent and selective small-molecule Bcl-2 inhibitor, it is not very effective against cancer cells that harbor high levels of Mcl-1, such as breast, lung, and melanoma cells." (PMID 24223823, 2013). "We also tested the role of Mcl-1 in regulating sensitivity of BRAFV600E melanoma cells to the combination of SAHA and PLX4720." (PMID 23744355, 2013). "Further, treatment of melanoma cells with Maritoclax showed significant decrease in Mcl-1 expression." (PMID 24223823, 2013). "For instance, the sensitization of melanoma cells to TRAIL-induced apoptosis and by inhibition of the MEK signalling pathway was associated with downregulation of Mcl-1." (PMID 24367627, 2013). "In melanoma cells, we demonstrate that prodigiosin activates the mitochondrial apoptotic pathway by disrupting MCL-1/BAK complexes." (PMID 23460874, 2013).